SLX9 (SLX9 ribosome biogenesis factor)
Description:
May be involved in ribosome biogenesis.
Synonyms: C21orf70; FAM207A; PRED56
Tractability: Small molecule: a structure with a bound ligand is known. PROTAC: ubiquitination databases record sites on it.
Gene: Protein-coding gene on chromosome 21 (44,939,938 to 44,977,014, forward strand). Ensembl gene ENSG00000160256.
Subcellular location: Nucleus, nucleolus
Subcellular location (Human Protein Atlas): Nucleoli; Nucleoplasm
Gene Ontology:
Molecular function: protein binding
Biological process: maturation of SSU-rRNA from tricistronic rRNA transcript (SSU-rRNA, 5.8S rRNA, LSU-rRNA)
Cellular component: nucleolus; 90S preribosome; preribosome, small subunit precursor
Genetic constraint (gnomAD): Loss-of-function variants: 22 observed, 21.54 expected, observed/expected ratio (o/e) 1.02, 90% interval 0.73 to 1.46. The upper end of that interval is the gene's LOEUF score, 1.46, which puts it in group 6 of 6, group 1 being the genes least tolerant of losing a copy. Missense variants: 299 observed, 272.83 expected, observed/expected ratio (o/e) 1.1, 90% interval 1 to 1.21. Synonymous variants: 113 observed, 108.27 expected, observed/expected ratio (o/e) 1.04, 90% interval 0.89 to 1.22.
Homologues: Orthologues: chimpanzee SLX9 (97% identical), macaque SLX9 (90% identical), pig SLX9 (73% identical), rat Slx9 (70% identical), mouse Slx9 (69% identical), guinea pig SLX9 (67% identical), dog SLX9 (57% identical), tropical clawed frog slx9 (42% identical), zebrafish slx9 (33% identical).
Diseases named in the same sentence as SLX9 in open-access papers:
SLX9 is named in the same sentence as 3 diseases in open-access papers, as found by Europe PMC text mining. Sharing a sentence is not in itself a finding about the gene and the disease.
SLX9 shares sentences with these, for which no sentence is quoted: tumor (2 papers); meningioma (1); osteosarcoma (1).